NRG3 (neuregulin 3)
Description:
Direct ligand for the ERBB4 tyrosine kinase receptor. Binding results in ligand-stimulated tyrosine phosphorylation and activation of the receptor. Does not bind to the EGF receptor, ERBB2 or ERBB3 receptors. May be a survival factor for oligodendrocytes.
Synonyms: Pro-NRG3; HRG3
Tractability: Antibody: UniProt places it where antibodies can reach, with medium confidence; UniProt predicts a signal peptide or a membrane-spanning region; its Gene Ontology location is reachable by antibodies, with medium confidence.
Safety:
Unwanted effects reported when the protein is acted on. In parentheses: how it was acted on, where the effect was seen, and who reports it.
adverse cardiovascular events (source: ClinPGx)
Gene: Protein-coding gene on chromosome 10 (81,875,194 to 82,987,179, forward strand). Ensembl gene ENSG00000185737.
Subcellular location: Cell membrane (Pro-neuregulin-3, membrane-bound isoform); Secreted (Neuregulin-3); Cell membrane (Isoform 3)
Subcellular location (Human Protein Atlas): Vesicles; Predicted to be secreted
Pathways (Reactome):
Signal Transduction: Downregulation of ERBB2 signaling; ERBB2 Activates PTK6 Signaling; ERBB2 Regulates Cell Motility; GRB2 events in ERBB2 signaling; Nuclear signaling by ERBB4; PI3K events in ERBB2 signaling; PI3K events in ERBB4 signaling; PI5P, PP2A and IER3 Regulate PI3K/AKT Signaling; PIP3 activates AKT signaling; RAF/MAP kinase cascade; SHC1 events in ERBB2 signaling; SHC1 events in ERBB4 signaling; Signaling by ERBB2; Signaling by ERBB4
Disease: Constitutive Signaling by Aberrant PI3K in Cancer; Signaling by ERBB2 KD Mutants; Signaling by ERBB2 TMD/JMD mutants
Gene Ontology:
Molecular function: receptor ligand activity; chemorepellent activity; growth factor activity; receptor tyrosine kinase binding; transmembrane receptor protein tyrosine kinase activator activity; signaling receptor binding
Biological process: ERBB4 signaling pathway; modulation of chemical synaptic transmission; animal organ development; intracellular signal transduction; regulation of cell growth; negative chemotaxis; nervous system development
Cellular component: extracellular region; glutamatergic synapse; plasma membrane
Genetic constraint (gnomAD): Loss-of-function variants: 31 observed, 65.82 expected, observed/expected ratio (o/e) 0.47, 90% interval 0.35 to 0.64. The upper end of that interval is the gene's LOEUF score, 0.64, which puts it in group 2 of 6, group 1 being the genes least tolerant of losing a copy. Missense variants: 905 observed, 896.1 expected, observed/expected ratio (o/e) 1.01, 90% interval 0.95 to 1.07. Synonymous variants: 392 observed, 367.22 expected, observed/expected ratio (o/e) 1.07, 90% interval 0.98 to 1.16.
Homologues: Orthologues: chimpanzee NRG3 (99% identical), macaque NRG3 (99% identical), pig NRG3 (96% identical), dog NRG3 (93% identical), rat Nrg3 (93% identical), mouse Nrg3 (92% identical), guinea pig NRG3 (72% identical), tropical clawed frog nrg3 (68% identical), zebrafish nrg3b (33% identical). Paralogues in human: NRG2 (17% identical), NRG1 (16% identical), NRG4 (5% identical).
Diseases named in the same sentence as NRG3 in open-access papers:
NRG3 is named in the same sentence as 58 diseases in open-access papers, as found by Europe PMC text mining. Sharing a sentence is not in itself a finding about the gene and the disease. The quoted sentences say what the papers report.
schizophrenia (35 papers, 2007 to 2025). A major psychotic disorder characterized by abnormalities in the perception or expression of reality. "One schizophrenia risk-associated polymorphism (rs10748842, an intron variant) in NRG3 was demonstrated through fMRI to impact prefrontal cortical physiology and was associated with elevated NRG3 gene expression in the adult and fetal prefrontal cortex." (PMID 39258169, 2024). "The NRG3 gene has been linked to schizophrenia in human genetic studies and Nrg3 knockout mice display behavioral deficits mirroring those observed in patients." (PMID 37779671, 2023). "NRG3 has been associated with several psychiatric illnesses, primarily schizophrenia but also MDD and bipolar disorder; however, the functional relevance of NRG3 remains poorly understood." (PMID 37432876, 2023). "A previous study by our group also showed that NRG3 polymorphism altered the effect of BMI on cognitive deficits of patients with schizophrenia." (PMID 35992594, 2022). "Genetic research in schizophrenia shows that risk variants in NRG3 are associated with cognitive and psychotic symptom severity, which is accompanied by increased expression of prefrontal cortical NRG3." (PMID 33897409, 2021). "As a specific ligand of receptor tyrosine kinase ErbB4, the structure and polymorphism of NRG3 are associated with neurodevelopmental disorders, including developmental retardation, cognitive impairment, autism and schizophrenia." (PMID 33897409, 2021). "NRG3 is located on chromosome 10q22-q23; variation in this locus predisposes individuals to schizophrenia as demonstrated by genome-wide studies." (PMID 32066712, 2020). "In the present study, we provided further evidence of genetic effects on cognitive impairment, showing that NRG3 polymorphism rs10748842 was associated with cognitive impairment, especially attention performance in schizophrenia." (PMID 32066712, 2020). "Our study demonstrated that NRG3 rs10748842 was associated with cognitive impairments, especially attention performance in schizophrenia." (PMID 32066712, 2020). "Further, some of these studies also demonstrated the specific association or opposite association between NRG3 gene mutations and cognitive inpatients in schizophrenia and healthy controls." (PMID 32066712, 2020). "Among them, Neuregulin 1 and Neuregulin 3 have been reported to contribute to an increased risk for developing schizophrenia." (PMID 24976857, 2014). "Mutations in Nrg3 have recently been reported to increase the risk for schizophrenia, and to alter activation of the PFC in humans." (PMID 25561905, 2014). "Genetic studies in schizophrenia demonstrate that risk variants in NRG3 are associated with cognitive and psychotic symptom severity, accompanied by increased expression of prefrontal cortical NRG3." (PMID 25093331, 2014). "This study confirms previously published associations between schizophrenia and NRG1 and ERBB4, and points to three other members of the NRG and ERBB gene families (EGFR, NRG2 and NRG3) as potential schizophrenia susceptibility genes." (PMID 17598910, 2007). "The NRG3 (10q23.1) gene belongs to the family of genes encoding neuregulin growth factors, which have been implicated in aberrant synaptic function and synaptogenesis in schizophrenia." (PMID 40631452, 2025). "Germline variants of NRG3 have been linked to mental disorders, such as schizophrenia." (PMID 37932833, 2023). "NRG3 has been implicated as a susceptibility gene for schizophrenia and schizoaffective disorders." (PMID 32023328, 2020). "In conclusion, our study demonstrated that genetic factor NRG3 rs10748842 might be associated with cognitive impairment, especially attention performance in schizophrenia." (PMID 32066712, 2020). "HOMER1, MAGI2, SLC1A3, NRG3 were associated with schizophrenia." (PMID 32993537, 2020). "A paralog of NRG1, Neuregulin-3 (NRG3) is another risk factor associated with schizophrenia." (PMID 26877878, 2016).
schizophrenia (continued). "Furthermore, schizophrenia risk-associated genetic variation in NRG3 impacts human prefrontal cortical physiology during working memory." (PMID 25093331, 2014). "We could not detect any significant influence of variation in the studied Neuregulin 1 and Neuregulin 3 polymorphisms on cognitive performance or on gamma noise power magnitudes in patients with schizophrenia." (PMID 24976857, 2014). "Contrary to our hypothesis, we could not detect any significant influence of variation in Neuregulin 1/Neuregulin 3 polymorphisms on cognitive performance or electrophysiological parameters of patients with schizophrenia." (PMID 24976857, 2014). "Many groups have demonstrated that genetic variants in the NRG3 gene are implicated in a range of neurodevelopmental and psychiatric disorders, including developmental delay, cognitive impairment, attentional deficits, and psychotic disorders such as schizophrenia." (PMID 39258169, 2024). "Thus, we reasonably investigated whether BMI affected cognitive impairment in schizophrenia was associated with NRG3 polymorphism rs10748842." (PMID 32066712, 2020). "While the function and processing of NRG3 have not been studied as well as its NRG1 homolog, their overlaps in similarity and function allow researchers to identify the roles of NRG3 identical to those of NRG1 in schizophrenia." (PMID 33897409, 2021). "By contrast, the mRNA levels of Nrg3 were reduced in GABAergic interneurons from schizophrenia PFC, compared with age- and sex-matched controls." (PMID 33436636, 2021). "Mice knocked out for Nrg3, exhibit behavioral analogs of schizophrenia, such as novelty-induced hyperactivity, impaired prepulse inhibition of the acoustic startle response and deficient fear conditioning." (PMID 34946848, 2021). "Other genes in this FOXP2 gene cluster include NRG3, ERBB4, DLX1, ROBO2, and ROBO2, all are susceptibility gene in schizophrenia and is related to development." (PMID 33658499, 2021). "Importantly, numerous independent studies have identified a genetic association of natural variants of NRG1, NRG3, and ErbB4 with schizophrenia, as well as with altered electrophysiological properties of inducible pluripotential stem cells isolated from schizophrenia patients." (PMID 32354758, 2020). "NRG3 is a strong candidate gene for schizophrenia, and neuregulin molecules and their receptors are involved in rat cardiac development and maintenance." (PMID 29765130, 2018). "We obtained DNA from 31 patients with schizophrenia and 23 healthy controls and analyzed NRG1 rs6994992, NRG1 rs3924999 and NRG3 rs10748842 promoter polymorphisms by allelic discrimination with real-time polymerase chain reaction (PCR)." (PMID 24976857, 2014). "This locus harbors Neuregulin3 (Nrg3), a member of the neuregulin family, which is important for nervous system development as well as schizophrenia." (PMID 25561905, 2014). "Like Grm3, Nrg3 (neuregulin 3) is a highly connected gene in ErGeN3 as well as a schizophrenia candidate gene." (PMID 22511924, 2012). "In a separate study on another Pakistani family, heterozygous missense variants NRG3 p.(Glu651Lys) and GRIN2A p.(Arg1169Trp) were co-inherited in patients with schizophrenia from unaffected consanguineous parents who were carriers for only one of either variant." (PMID 36384485, 2022). "Visibly, NRG3 follows NRG1 into the spotlight of schizophrenia research, showing that the influence of genetic variation may exert on the specificity of a phenotype in addition to the risk for this disease." (PMID 33897409, 2021). "Further, BMI might affect cognitive function under certain NRG3 rs10748842 genotype in schizophrenia, suggesting that NRG3 rs10748842 might contribute to the effects of BMI on cognitive impairment in chronic patient with schizophrenia." (PMID 32066712, 2020).
schizophrenia (continued). "In present study, we aimed to determine whether possession of the NRG3 rs10748842 influences the correlation between elevated BMI and reduced cognitive ability in schizophrenia." (PMID 32066712, 2020). "Moreover, NRG3 rs10748842 altered the effect of BMI on cognitive impairments as measured by the RBANS language score in chronic patients with schizophrenia." (PMID 32066712, 2020). "Of these pathways, schizophrenia appears to have to strongest link to the Nrg/ErbB pathway, and SNPs in several of the genes encoding Nrg (NRG1, NRG2, NRG3, and NRG6) and all of the genes encoding ErbB receptors (EGFR, ERBB2, ERBB3, and ERBB4) have been linked to schizophrenia." (PMID 30618607, 2018). "Nrg3 is a critical mediator in the assembly of cortical inhibitory circuits and balance of ex-inhibition, which is hypothesized as pathophysiology schizophrenia." (PMID 28993723, 2017). "Gene-gene interaction between NRG1 and NRG3 has also been observed in a schizophrenia study, and according to the NCBI BioSystems database, NRG3 may also be involved in the immune system." (PMID 25919455, 2014). "NRG3 is a neurotrophic factor, a specific ligand for the receptor tyrosine kinase ErbB4 and a paralog of the growth factor NRG1, all of which are strong candidate risk genes for schizophrenia." (PMID 25093331, 2014). "In addition to providing further evidence of NRG1 and ERBB4 associations to schizophrenia, our study is the first to suggest possible involvement of three additional genes from the NRG and ERBB gene families, i.e. NRG2, NRG3 and EGFR (ERBB1)." (PMID 17598910, 2007). "More interestingly, when performing genotypic stratification analysis, we found a positive association between BMI and language score only in TT patients, but not in CT + CC genotypes, indicating that the interaction between NRG3 and BMI might affect cognitive function in schizophrenia." (PMID 32066712, 2020). "We could not detect any significant influence of variation in NRG1/NRG3 polymorphisms on the cognitive performance of patients with schizophrenia." (PMID 24976857, 2014). "Neuregulin 3 (NRG3), a specific ligand for ErbB4 and a neuronal-enriched neurotrophin is implicated in the genetic predisposition to a broad spectrum of neurodevelopmental, neurocognitive and neuropsychiatric disorders, including Alzheimer's disease, autism and schizophrenia." (PMID 25093331, 2014). "Furthermore we demonstrate how perturbations in NRG3 expression at distinct developmental stages may contribute to the neurological deficits observed in brain disorders such as schizophrenia and autism." (PMID 25093331, 2014). "Neuregulin 3 (NRG3), a paralog of NRG1, is a molecule of increasing interest, due to its link to psychiatric disorders that includes schizophrenia." (PMID 26877878, 2016). "Additionally, in agreement with convergent evidence suggesting altered NRG3 expression is pathophysiologically relevant in normal brain function, NRG3 expression is elevated in the PFC of patients with schizophrenia, compared to unaffected individuals." (PMID 25093331, 2014).
Cognitive impairment (8 papers, 2020 to 2026). Abnormal cognition is characterized by deficits in thinking, reasoning, or remembering. "Both are implicated in cell proliferation and differentiation; NRG3 has been implicated in cognitive impairment." (PMID 38167548, 2024). "Genetics have identified certain susceptibility loci, including neurotransmitter (e.g., NMDA and NMDAR) and cytokine-related genes (e.g., NRG3), to be significantly associated with cognitive impairment." (PMID 36406755, 2022). "The NRG3 gene at 10q22-q24 has been implicated in multiple psychiatric traits, such as cognitive impairment." (PMID 34220946, 2021). "NRG3 gene at 10q22–q24 has been implicated in multiple psychiatric traits such as cognitive impairment." (PMID 33897409, 2021). "Previous evidence indicated that NRG3 gene mutations were correlated with cognitive impairment in patients with schizophrenia." (PMID 32066712, 2020). "However, further mechanism on interplay of NRG3 and BMI in cognitive impairments should be investigated in future." (PMID 32066712, 2020). "Additionally, several pathways including the ERBB4 signaling pathway (adjusted p = 2.82 × 10-3), driven by ERBB4, NRG1, and NRG3 may contribute to cognitive impairments." (PMID 42193047, 2026).
bipolar disorder (7 papers, 2017 to 2023). A disorder of the brain that causes unusual shifts in mood, energy, activity levels and the ability to carry out day-to-day tasks. "While NRG2 and NRG3 complexes have not been linked to ASD, many reports support their link to other neurodevelopmental disorders such as SCZ and bipolar disorder." (PMID 35501678, 2022).
Anxiety (5 papers, 2014 to 2024). Intense feelings of nervousness, tension, or panic often arise in response to interpersonal stresses. "During nicotine withdrawal, an increase in neuregulin 3 appears to mediate the synaptic plasticity that underlies anxiety-associated symptomology." (PMID 33828466, 2021). "Additionally, SNPs in NRG3 have been linked to nicotine addiction and smoking cessation success in humans, translated from mice studies showing ErbB4 to play a role in anxiety-like behaviors during nicotine withdrawal." (PMID 39258169, 2024). "Of notice, genes associated to differentially methylated clusters included the acid sensing ion channel subunit 2 (Asic2) gene, relevant to both acidification detection and anxiety, and Neuregulin 3 (Nrg3) gene, associated with “neurogenesis”, “cell motility” terms." (PMID 29396481, 2018). "Neuregulin 3; involved in intracellular signaling, nicotine-related anxiety symptomology CAMP responsive element binding protein; involved in the stimulation of the cAMP pathway, nicotine-mediated responses, and withdrawal symptoms." (PMID 33828466, 2021). "NRG3 overexposure during the neonatal period had lifelong effects on anxiety in adulthood as demonstrated by increased time spent in the center of the open field arena." (PMID 25093331, 2014). "Here we provide novel evidence, that peripherally injected NRG3 can cross the BBB of neonatal mice, and that overexposure to NRG3 during early postnatal life leads to alterations in anxiety-like and social behaviors in adulthood." (PMID 25093331, 2014). "This suggests that NRG3 is critical in the expansion of neurocircuitry involved in anxiogenesis during early postnatal development, however, further studies employing more sophisticated measures of anxiety such as elevated plus maze are warranted." (PMID 25093331, 2014). "Together, our data suggest that NRG3 plays a prominent role in early postnatal brain development where it potentially modulates the construction and plasticity of newly developing brain circuits relevant to anxiety and social cognition." (PMID 25093331, 2014). "Moreover, NRG3 overexposure during early neonatal development had life-long consequences on discrete behavioral phenotypes, namely those indicative of anxiety and social development." (PMID 25093331, 2014). "While anxiety was not assessed in adult mice neonatally overexposed to NRG1, peripheral exposure to NRG1 in adult mice induces an anxiolytic phenotype, therefore, it is possible that NRG3 may also have temporally regulated effects." (PMID 25093331, 2014).
breast carcinoma (5 papers, 2016 to 2025). "Whereas NRG3 is potentially overexpressed in breast cancer, paradoxically, recombinant NRG3 diminished the growth of human breast cancer cells in vitro." (PMID 35846378, 2022). "Ectopic expression of NRG3 was detected in a proportion of primary breast cancer biopsies (42%) with undefined function." (PMID 27449290, 2016). "In human breast cancer cell lines, NRG3 activates ectopically-expressed ERBB receptors (ERBB1-4)." (PMID 35846378, 2022). "High levels of NRG3 are detected in the NSCLC cell lines NCI-H522, H661, NCI-H1155, NCI-H1299, and the control MCF7 breast cancer cells." (PMID 41007372, 2025). "Parathyroid hormone-related protein (PTHrP), NRG3, and GLI3 are additionally recognized as having a role in breast cancer pathogenesis and prognosis." (PMID 40001874, 2025).